CXCR6 (C-X-C motif chemokine receptor 6)
Diseases named in the same sentence as CXCR6 in open-access papers (continued):
Sharing a sentence is not in itself a finding about the gene and the disease.
COVID-19 (continued). "Next, we compared expression of markers associated with cell activation (CD40), maturation (CD16), homing (CXCR6), tissue recruitment (CD62L), and polarization (CD163) on monocytes and DC subsets in young and aged COVID-19 patients relative to healthy donors." (PMID 34707619, 2021). "The role of CXCR6, as well as of CCR5 and CXCR4, in MAIT cell recruitment in COVID-19, and in COVID-19 in general, is currently unclear and should be topics of future investigation." (PMID 32989174, 2020). "This includes CXCR6, which is consistently expressed by MAIT cells in HDs and largely remains expressed in COVID-19 albeit with somewhat lower expression in patients with reduced MAIT cell frequencies." (PMID 32989174, 2020). "The number of CD4+ CXCR6+ T cells was reduced in the blood of patients with severe COVID-19 compared to those with a negative viral load." (PMID 37762093, 2023). "Chemokine receptors, such as CCR9, CXCR6, CCR1, CCR3, CCR5, and CCR2, are all located on chromosome 3 and already showed significant associations with COVID-19 without network boosting." (PMID 36291657, 2022). "CXCR6+ memory CD8+T cells exhibit a notable polyfunctionality including high expression of cytokines and chemokines, as well as enhanced activation and proliferation of T cells in severe COVID-19 patients." (PMID 35172892, 2022). "Indeed, our analysis of RNA-seq data from BAL fluid of COVID-19 patients suggest a CXCR3- and CXCR6-mediated recruitment of NK cells and T cells, as well as a CCR5-mediated recruitment particularly of CD8+ T cells in moderate disease." (PMID 35371005, 2022). "Together, our results indicate a role for CXCR3+, CXCR6+, and/or CCR5+ NK cells and T cells that potentially migrate to the lungs in moderate COVID-19 and influenza patients, identifying common targets for future therapeutic interventions in respiratory viral infections." (PMID 35371005, 2022). "Finally, two GWAS have identified the loci 3p21.31 (LZTFL1, SLC6A20, CCR9, FYCO1, CXCR6, and XCR1) and 9q34.2 (ABO) with COVID-19 severity." (PMID 33868239, 2021). "Other studies have identified CXCR3, CXCR6, and CCR5 as other potential mediators of immune cell trafficking to the lungs during COVID-19 infection, and one of these studies also demonstrated that T and NK cells that expressed these receptors in COVID-19 patients showed greater signs of activation." (PMID 36817450, 2023). "Consequently to the proposed involvement of HHcy in COVID-19, it was suggested that Hcy may contribute to severe COVID-19 by interfering with G-protein-coupled receptors (GPCRs) (AT1R, B2 and CXCR6), by their upregulation, being an alternative agonist and inducing their heteromerization." (PMID 35456998, 2022). "Together, these results demonstrate common activation patterns between NK cell subsets in COVID-19 and influenza patients, with a stronger activation of NK cells expressing CXCR3, CXCR6, CCR2, and/or CCR5 than NK cells lacking any lung-homing receptors." (PMID 35371005, 2022).
breast cancer (34 papers, 2009 to 2026). A primary or metastatic malignant neoplasm involving the breast. "The retention of CXCR6+CD8+TRM cells has been reported to be mediated by CXCR16 secreted by breast cancer cells, and the deficiency of CXCR6 promotes the egress of CD8+TRM cells out of tumor tissues." (PMID 40066223, 2025). "CXCL16, which recruits CXCR6 expressing Th1 and CD8+ effector T cells, is upregulated by both mouse and human breast cancer cells; CXCR6 deficient mice experienced impaired tumor regression and decreased CD8+ T cell infiltration after irradiation." (PMID 30895168, 2019). "For example, anti-CXCL16 blockade in mouse breast cancer liberates CXCR6+ effectors from primary tumors, driving their migration and differentiation into lung TRM cells (see Section 3) and highlighting a promising target for TRM-directed therapies." (PMID 40862776, 2025). "In most cancers (melanoma, head and neck cancer, lung adenocarcinoma, and breast cancer), patients with high CXCR6 expression had a greater survival probability." (PMID 36311728, 2022). "The genes sharing these GO terms have been previously shown to be involved in breast cancer prognostic process (e.g., CXCR6, KIT, RUNX3) and also immune cell regulation (e.g., CD8B, DAPP1, LY75)." (PMID 33919884, 2021). "Irradiation induces the expression of CXCL16 in breast cancer cells, enhancing the migration of NK cells with high CXCR6 expression to kill tumor cells." (PMID 33763372, 2021). "In a previous study, irradiation was reported to induce CXCL16 chemokine expression in cancer cells and to enhance the migration of CXCR6+ natural killer cells to breast cancer cells for their destruction." (PMID 31715586, 2019). "Consistent with previous reports, we found that CXCL16 and CXCR6 were coexpressed in breast cancer cells but to inverse extent." (PMID 24864132, 2014). "Disrupting this axis-for instance, by PFKP inhibition or CXCL16/CXCR6 blockade-may restore TA sensitivity in aggressive basal-type breast cancer, offering a promising strategy to improve long-term outcomes for hard-to-treat patients." (PMID 42024199, 2026). "Furthermore, the other three hub genes, IL2RB, XCR1 and CXCR6, have been reported to be related with the prognosis of other cancers, such as early breast cancer, salivary adenoid cystic carcinoma, bladder and hepatocellular cancers." (PMID 33719152, 2021). "The effect of CXCL16 on cancer cell migration may be increased by chronic hypoxia, which increases HIF-1-dependent CXCR6 expression and thus the sensitivity of tumor cells to sCXCL16, as shown in breast cancer MDA-MB-231 cells." (PMID 33800554, 2021). "Also, CXCR6 expression is increased by chronic hypoxia in breast cancer MDA-MB-231 cells and HUVEC, with this effect dependent on HIF-1 regulation." (PMID 33800554, 2021). "CXCL12/CXCR4 and CXCL16/CXCR6 chemokine signaling also mediates breast cancer progression." (PMID 32879136, 2020). "Moreover, CXCL16 via interaction with CXCR6 is capable of increasing cell migration, invasion, and metastasis in breast cancer." (PMID 31698786, 2019). "Expression of CXCR6 shows a higher epithelial staining in breast cancer nest site and metastatic lymph node than the normal breast tissue, suggesting that CXCR6 may be involved in breast cancer (BC) development." (PMID 25909173, 2015). "Our previous studies demonstrate that CXCL6/CXCR6 chemokine axis induces prostate cancer progression by the AKT/mTOR signaling pathway; however, its role and mechanisms underlying invasiveness and metastasis of breast cancer are yet to be elucidated." (PMID 25909173, 2015). "However, another study found that CXCR6 could increase cell migration, invasion, and metastasis of breast cancer." (PMID 35505821, 2022). "Recently, Cheng's studies indicate that different invasive breast cancer (BC) cell lines express CXCR6 at different levels, positively correlated with its invasive ability; however, whether CXCR6 plays a role in BC invasion and metastasis is still kept unclear." (PMID 25909173, 2015).
breast cancer (continued). "In a 4T1 breast cancer model, using antibodies to neutralize intratumoral CXCL16 not only liberated CXCR6+ effector-memory cells from the primary tumor but also led to their accumulation as CD103+CD69+ TRM cells in the lungs." (PMID 40862776, 2025). "CXCR6, the receptor for CXCL16, is induced in breast cancer cells by hypoxia, and was found to be expressed in lymph metastasis from breast cancer patients." (PMID 38055067, 2023). "Phenotypic analysis of the markers we identified by scRNAseq revealed that expression of CXCR6, ICOS, JAML, NK1.1, NKG2D, and PD-1 by Vγ4+ and Vγ6+ cells remains unaffected by mammary tumor conditioning." (PMID 36480166, 2023). "In another preclinical model of lung metastases from breast cancer, it has been shown that CXCR6- T effectors are the major subset preferentially egressing the tumor to form distant CXCR6+ TRM, whereas intratumoral CXCR6+ T cells are retained in the tumor." (PMID 36311728, 2022). "High levels of CXCL12 and CXCL16 in CAFs from human brain cancer metastasis attract breast cancer cells via the CXCR4/CXCL12 and CXCR6/CXCL16 pathways." (PMID 33096815, 2020). "To further investigate the importance of chemokines CXCL12 and CXCL16 secreted by metastatic CAFs on breast cancer cell migration, we analyzed the expression of cognate chemokine receptors CXCR4 and CXCR6 on patient-derived cancer cells." (PMID 28649646, 2017). "CXCR6/CXCL16 has also been described as an oncogenic axis in a variety of solid cancers, such as papillary thyroid carcinoma, gastric, prostate, and breast cancer, through positive regulation of survival pathways such as ERK." (PMID 27585840, 2016). "The interaction between CXCL6 secreted by breast cancer cells and CXCR6 on naïve MSCs leads to the induction of CXCL10 secretion by MSCs, which in turn acts on CCR3 on breast cancer cells, facilitating the recruitment of MSCs and promoting breast cancer metastasis." (PMID 40676710, 2025). "FACS analysis showed that patient-derived breast cancer cells expressed both CXCR4 and CXCR6." (PMID 28649646, 2017). "The screening results showed that none of the receptors for Cx3cl1 (CX3CR1), Cxcl16 (CXCR6), Ccl17 (CCR4, DARC, CCR10) or IL6 (IL6R) was more expressed in basal B compared to basal A or luminal breast cancer cells." (PMID 38055067, 2023).
melanoma (31 papers, 2009 to 2025). A malignant, usually aggressive tumor composed of atypical, neoplastic melanocytes. "Cxcr6- deficient mice or CXCL16 neutralizing Ab resulted in an enhanced metastasis to the liver by B16 melanoma cells or Lewis Lung tumor cells." (PMID 36311728, 2022). "CXCR6 also positions tumor reactive CD8+ TRM with CXCL16+ DC clusters in the skin of melanoma-associated vitiligo, which favor their persistence." (PMID 36311728, 2022). "In glioblastoma or melanoma cells, CXCR6 activates the mCXCL16→ERK MAPK pathway, which causes migration but not proliferation of tumor cells." (PMID 33800554, 2021). "More recently, expression of CXCR6 was associated with human tumors, including melanoma." (PMID 21203549, 2010). "The first one is the first phenotypic evidence to support the origin of melanoma cancer stem cells (CSCs) from mutated tissue-specific stem cells; and the second one is the identification of a more aggressive subpopulation of CSCs in melanoma that are CXCR6+." (PMID 21203549, 2010). "Consistently, elevated expression of CXCL-16 and its receptor, CXCR6, has emerged as a strong predictor of overall survival in melanoma patients." (PMID 40869222, 2025). "It has been demonstrated that the anti-tumor efficacy of T cells in melanoma hinges upon the involvement of CXCR6-expressing CD8+ T cells." (PMID 39835121, 2024). "In bulk melanoma cohort, we found that the expression level of CXCR6 are elevated in post-treatment stage compared with baseline stage." (PMID 37593098, 2023). "In a preclinical model of melanoma and colorectal cancer, anti-PD-1 treatment significantly increased CXCR6 expression on infiltrating CD8+ T cells." (PMID 36311728, 2022). "The ABC transporters family tumourigenic potential is also supported by C-X-C motif chemokine receptor 6 (CXCR6) expression, another melanoma CSCs marker, particularly associated with asymmetric self-renewal." (PMID 35334544, 2022). "Recent studies have also identified CXCR6 on skin effector T cells in the context of melanoma and on skin resident memory T cells (Trm) in melanoma-associated vitiligo." (PMID 35833127, 2022). "The CXCR6/CXCL16 axis is pro‐inflammatory, CXCR6 is expressed by a self‐renewing subset of melanoma stem cells, and melanoma secretes CXCL16, contributing to CXCR6‐mediated leukocyte recruitment." (PMID 34129290, 2021). "In melanoma, CXCR6 is overexpressed in primary and metastatic melanoma, and CXCR6 positive cells are identified as cancer stem cells and can self-renew but also generate other tumor cells." (PMID 33031392, 2020). "For example, CXCR4 receptor is expressed in tumors such as ovary, glioma, melanoma and renal, CXCR6 in prostate cancer, CXCR2 in melanoma and CCR6 in colorectal and pancreatic cancer." (PMID 32499779, 2020). "In the next step, we stimulated stably CXCL16 expressing LOX melanoma cells (LOX-CXCL16) with recombinant CXCR6 and observed again an activation of ERK1/2 (upper part)." (PMID 28698473, 2017). "A similar correlation has been demonstrated in patients with gliomas, nasopharyngeal tumors, rectal cancer, colorectal cancer, and melanomas, suggesting that CXCR6 expression is important for invasion and metastasis of multiple tumors." (PMID 25909173, 2015). "Markers focusing on functional properties of stem cells like CXCR6 are expressed by human melanoma cell lines and melanoma tissue." (PMID 27429260, 2014). "In recent publications, one of us identified aggressive subpopulations expressing two stem cell markers, ABCG2 and CXCR6, in human melanoma cell lines, making this tumor a suitable candidate to test our theory." (PMID 22275856, 2012). "Recently, others and we demonstrated that the ASRA protein, Cxcr6, is expressed by human melanoma cancer stem cells." (PMID 21818293, 2011). "In this regard, it is important to emphasize that our analysis of human melanoma biopsies confirmed the presence of a ABCG2+/CXCR6+ subfraction in human tissues." (PMID 21203549, 2010).
melanoma (continued). "We looked for co-association of CXCR6 expression and ABCG2 expression with MCSC activity and evidence for the descent of melanoma CSCs from TSSCs." (PMID 21203549, 2010). "RT-PCR analysis of Melanoma Associated Antigens (MAA) expressed by melanoma cell lines IGR37 and IGR39 sorted for its expression of CXCR6 and double positive ABCG2/CXCR6 IGR37 cells and in tumor xenograft engrafted with CXCR6+ IGR37 cells." (PMID 21203549, 2010). "In vivo CXCR6+ melanoma cells produced a tumor in less time than ABCG2+ cells and, more interestingly, the negative subpopulation did not give a tumor." (PMID 21203549, 2010). "CXCR6 identifies a more discrete subpopulation of cultured human melanoma cells with a more aggressive MCSC phenotype than cells selected on the basis of the ABCG2+ phenotype alone." (PMID 21203549, 2010). "CXCR6 enhances the response of colorectal cancer and melanoma cells to PD-1 blockade treatment." (PMID 38698468, 2024). "CXCR6 was upregulated in the melanoma anti-PD-1 immunotherapy signature, indicating a potential shift toward a proinflammatory tumor microenvironment, which could lead to subsequent metastasis." (PMID 38023136, 2023). "In bulk melanoma cohort and IMvigor210 cohort (metastatic urothelial cancer), we also found that anti-PD-1 therapy could significantly enhance the expression of CXCR6, especially in responders." (PMID 37593098, 2023). "Chemokine CXCL16 and its T cell ligand CXCR6 are also key propagators of melanoma." (PMID 34129290, 2021). "The specificity of reverse signaling was proven by silencing experiments, as well as by transfection experiments using a CXCL16-negative, CXCR6-negative melanoma cell line to investigate intracellular signaling and biological effects upon stimulation with CXCR6." (PMID 28698473, 2017). "Moreover, like ABCG2-expressing melanoma cells, CXCR6-expressing cells are a small fraction of cells in cultures of primary, metastatic melanoma cell lines and human melanoma biopsy specimens." (PMID 21203549, 2010). "In addition, to the role of CXCR6 in the immune response, more recently, CXCR6 expression has been reported in some human tumors, including melanoma." (PMID 21203549, 2010). "Although the evaluated melanoma cell lines were derived from human tumor tissues, the newly described CXCR6+/ABCG2+ cell phenotype might have been limited to cultured tumor cells." (PMID 21203549, 2010). "Therefore, we investigated 4 uncultured human melanoma positive lymph node biopsy specimens for the presence of cells with the CXCR6+/ABCG2+ phenotype." (PMID 21203549, 2010). "Studies on patients show that CXCR6 expression is greater in metastasis than in primary tumors of such cancers as cervical cancer, Ewing sarcoma family tumor, gastric cancer, melanomas, nasopharyngeal carcinoma, ovarian carcinoma, papillary thyroid cancer, and prostate cancer." (PMID 33800554, 2021). "Also, CXCR6 expression is greater in metastasis than in the primary tumor, such as in cervical cancer, Ewing sarcoma family tumor, gastric cancer, melanomas, nasopharyngeal carcinoma, ovarian carcinoma, papillary thyroid cancer, and prostate cancer." (PMID 33800554, 2021). "Additionally, we used LOX melanoma cells to generate stable clones expressing CXCR6 (LOX-CXCR6)." (PMID 28698473, 2017). "Finally, we have characterized the subpopulation ABCG2+/ABCG2- and CXCR6+/CXCR6- of melanoma for the expression of melanoma associated antigens (MAA) in view of a possible immunotherapeutic approach against more aggressive subpopulations expressing ABCG2 and/or CXCR6." (PMID 21203549, 2010). "Chemokines secretion (CXCR6, CXCL9, CCL5, and CCR5) was also shown to predict response to anti–PD-1–directed therapy in melanoma patients." (PMID 37875556, 2023). "CXCR6 is expressed in more aggressive CSC and is a marker of CSC asymmetric self-renewal division, as shown in melanoma cells." (PMID 33800554, 2021).